MIR6873 (microRNA 6873)
Synonyms: hsa-mir-6873
Gene: MicroRNA gene on chromosome 6 (33,287,227 to 33,287,289, reverse strand). Ensembl gene ENSG00000284517.
Homologues: Orthologues: chimpanzee MIR6873 (100% identical).